NOX4 (NADPH oxidase 4)
Diseases named in the same sentence as NOX4 in open-access papers (continued):
Sharing a sentence is not in itself a finding about the gene and the disease.
infection (continued). "In the result of RGNNV infection did not increase the Nox4 protein level (data not shown), which may meant complex I and complex III are more predominately to produce ROS in this fish cells with RGNNV infection." (PMID 21991373, 2011). "Transcriptomic analyses revealed a negative ROS balance in Camp-/- littermates colons during infection, with lesser synthesis of key ROS enzymes, such as NADPH oxidases (Nox4 and Duox2), and increased ROS detoxification." (PMID 40735968, 2025).
cardiac disease (14 papers, 2017 to 2025). "Building on the mechanistic evidence presented in Section 4, where the causal role of NOX4 in cardiac disease was established using transgenic and knockout models, this chapter examines NOX4 as a therapeutic target." (PMID 41009041, 2025). "The importance of NOX4 splice variants extends beyond lung and vascular cells, as a more recent work has also highlighted their relevance in cardiac disease." (PMID 41009041, 2025). "High levels of TGF-β as well as activation of both NOX-2 and NOX-4 have also been associated with cardiac disease, in particular with AF." (PMID 36077591, 2022). "On the other hand, and more recently, NOX4 has emerged as an adaptative protein involved in the cellular stress response, with increased NOX4 expression and/or activity linked to beneficial effects in the context of cardiac diseases." (PMID 41009041, 2025). "However, a key question remains: does increased NOX4 expression contribute directly to detrimental cardiac outcomes, or instead does it reflect a compensatory mechanism aimed at reversing adverse remodeling associated with heart diseases?" (PMID 41009041, 2025). "Overall, these preclinical and clinical findings demonstrate the pathological roles of NOX4 in various heart diseases, where its increased activity contribute to disease progression, thereby supporting NOX4 as a promising therapeutic target." (PMID 41009041, 2025). "Taken together, indirect inhibition of NOX4 consistently attenuates oxidative stress, fibrosis, and contractile dysfunction across diverse preclinical models of cardiac diseases." (PMID 41009041, 2025). "Moving forward, balancing NOX4’s harmful and beneficial functions will be key to successful heart disease therapies." (PMID 41009041, 2025). "In the present review, we examine preclinical and clinical evidence supporting both the harmful and protective roles of NOX4 in cardiac function, across several major cardiac diseases." (PMID 41009041, 2025). "Inhibition or knockout of NOX4 has shown promise in mitigating these pathological changes, suggesting that NOX4 represents a potential therapeutic target for treating heart disease." (PMID 41009041, 2025). "Prior experiments had reported that genetic deletion or pharmacological inhibition of NOX2 or NOX4 reduced ROS production and infarct size in the context of cardiac disease 33,34." (PMID 32398964, 2020). "The role of NOX4 in the heart has been characterized in various cardiac disease models with the use of systemic and/or cardiomyocyte-specific NOX4 overexpression or deletion animal models." (PMID 32923955, 2019). "While there have been conflicting reports of the impact of NOX4 in mouse models of cardiac pressure overload, the coincident upregulation of NOX4 with cardiac disease is highly suggestive that NOX4-mediated ROS production contributes to disease pathogenesis." (PMID 31857574, 2019). "Given Nox4 a critical mediator in the pathologies of heart diseases, there are urgent needs to discover novel potential molecular diversity targeting Nox4." (PMID 28230797, 2017). "Given the critical role of NOX4 in promoting cardiac fibrosis and other forms of cardiac dysfunction, targeting NOX4 may offer therapeutic potential for heart diseases." (PMID 41009041, 2025). "Despite extensive research, the specific role of NOX4 in cardiac diseases remains controversial." (PMID 41009041, 2025). "In addition, in experimental models of cardiac diseases, overexpression of cardiac NOX4 has also been shown to improve cardiac function, both in vivo and in vitro." (PMID 41009041, 2025). "Nox4 is an important mediator in the pathogenesis of heart disease." (PMID 36675993, 2022). "In addition to respiratory chain dysfunction-mediated ROS dysregulation leading to cardiac disease, genetic models targeting p66shc, MAO, and NOX4 also support a specific role for mitochondrial ROS in cardiac disease." (PMID 31857574, 2019).
cardiac disease (continued). "Studies also indicate that other signaling molecules such as NADPH oxidase 4 (NOX4) and GPX4 regulate ferroptosis and thus affect heart disease." (PMID 34901035, 2021). "Research using rabbits with heart disease has shown that NOX4 interacts with Smad 2/3 to regulate TGF-β signalling thereby indirectly determining fibroblast to myofibroblast differentiation and inhibition of NOX4 was shown to have the potential as an efficacious therapy for heart disease." (PMID 39480826, 2024).
metabolic disease (11 papers, 2013 to 2025). A congenital disorder (due to inherited enzyme abnormality) or acquired (due to failure of a metabolically important organ) disorder resulting from an abnormal metabolic process. "PKC/Nox4 overactivation has been linked with excessive ROS production and relates to the development of metabolic diseases." (PMID 35431967, 2022). "Furthermore, our results suggest that the mutation of NOX4 gene could cause the functional reduction of hippocampal memory and learning ability under human metabolic diseases." (PMID 32438638, 2020). "Although some studies point toward a crucial role of Nox4 enzymes in adipose tissue dysfunctions, as well as metabolic disorders, this has been mainly related to the weight gain associated with this conditions." (PMID 29167640, 2017). "NOX4 may regulate ferroptosis progression through the O-GlcNAcylation of proteins, potentially linking NOX4-mediated metabolic disorders with ferroptosis." (PMID 39867658, 2024). "In mammals, NADPH oxidase 4 is constitutively expressed in immune and epithelial cells, contributing to host defence as well as redox-sensitive signalling pathways, such as NF-κB, MAPK, and JNK—processes implicated in inflammation, fibrosis, and metabolic disease." (PMID 41141596, 2025). "Additionally, NOX4 might be an important gene for the maintenance of hippocampal function during human metabolic diseases." (PMID 32438638, 2020).
kidney (10 papers, 2014 to 2023). "Statins downregulated protein and mRNA expression of NOX2/NOX4 and improved mitochondrial function, by which statins suppressed ROS production and prevented cholesterol-induced kidney injuries." (PMID 35562673, 2022). "The elevation of NOX4 expression was also observed 12–24 h after performing transient middle cerebral artery occlusion in another study." (PMID 31504040, 2019). "NOX-4, predominantly expressed in the kidney is playing a major role in the kidney fibrosis." (PMID 32994511, 2020). "Indeed, in this study, we show that the increase in mitochondrial ROS in the diabetic kidney is not observed in the absence of Nox4, a finding consistent with recent reports of the presence of Nox4 in the mitochondria." (PMID 25367693, 2014).
neurodegenerative disease (9 papers, 2015 to 2025). A disorder of the central nervous system characterized by gradual and progressive loss of neural tissue and neurologic function. "As one of the isoforms of NADPH oxidase, Nox4 produces large amounts of ROS, leading to oxidative stress, which is linked to numerous neurodegenerative diseases." (PMID 37875930, 2023). "So far, it has been confirmed that NOX4 is responsible for a significant generation of ROS in the brain and an increase in its activity has been implicated in the development of neurodegenerative diseases, both acute and chronic." (PMID 32182821, 2020). "We demonstrate that NOX4 is a key player in NLRP3 inflammasome activation suggesting NOX4 pharmacological inhibition as a potent therapeutic approach in neurodegenerative diseases." (PMID 37760032, 2023). "NOX1, 2, and 4 are the main NOX subtypes expressed in neurons, while the role of NOX2 and NOX4 in neurodegenerative diseases has been relatively well studied." (PMID 33644049, 2021). "Hence, we here validate NOX4 as a key player in NLRP3 inflammasome activation, suggesting NOX4 pharmacological inhibition as a potent therapeutic approach in neurodegenerative diseases." (PMID 37760032, 2023). "We here validate NOX4 as a key player in NLRP3 inflammasome activation, suggesting NOX4 pharmacological inhibition as a potent therapeutic approach in neurodegenerative diseases." (PMID 37760032, 2023). "NOX1, NOX2, and NOX4 are the major subtypes of NOX in the central system that play a major role in brain injury and neurodegenerative diseases." (PMID 33644049, 2021).
inflammation (8 papers, 2013 to 2024). Aberrant reaction of the microcirculation characterized by movement of fluid and leukocytes from the blood into extravascular tissues. "NOX1 and NOX4 have been shown to be associated with inflammation related diseases in recent reports." (PMID 36009258, 2022). "Similarly, the endothelial-specific overexpression of Nox4 attenuates atherosclerotic remodeling and vascular inflammation in ApoE−/− mice, while the loss of Nox4 promotes the formation of atherosclerotic lesions and vascular inflammation." (PMID 36139898, 2022). "Whether NOX1 and NOX4 are involved in the TNF-α-induced lung inflammation needs to be investigated in the future." (PMID 23671702, 2013). "Therefore, we speculate that increased ROS formation by Nox4 may enhance the function of tubular TRPV1 in terms of renal inflammation." (PMID 34201387, 2021). "Studies using the BEAS-2B cell model have shown that kaempferol reduces the expression of nicotinamide adenine dinucleotide phosphate oxidase 4 (NOX4) and suppresses TNF-α-induced airway inflammation." (PMID 39596066, 2024).
neurological disorders (6 papers, 2020 to 2024). "Because the elevation of NOX4 has been implicated in neurological disorder-associated free radical generation, our findings suggested that the elevation of NOX4 and reduction of Nrf2/HO-1 are causes of PCS-induced oxidative stress." (PMID 32932690, 2020). "We also incorporated NOX4, anticipated as a notable indicator in various neurological disorders." (PMID 39170638, 2024). "To evaluate the effect of NOX4 within a dysfunctional network as seen in neuroinflammation or during epileptic activity, we choose a model of hyperexcitability in vivo that renders the dysfunctionality within the neurological disease." (PMID 37081190, 2023). "NOX2 is the main source of ROS in phagocytes; however, NOX1-and NOX4-dependent ROS productions may occur in microglia of different neurological diseases." (PMID 36278207, 2022).
bacterial infection (3 papers, 2010 to 2020). "Here we for the first time report Nox4 expression by intestinal epithelial cells and demonstrate Nox4-mediated ROI production in response to bacterial infection." (PMID 21124989, 2010).
proliferative retinopathy (2 papers, 2017 to 2024). "Studies in a mouse model have demonstrated that Nox1 knockout, but not Nox2 or Nox4 knockout, protects the retina against oxygen-induced retinopathy and identifies microglia as the source of hypoxia-induced ROS generation and neovascularization." (PMID 38612560, 2024).
respiratory disease (2 papers, 2022 to 2025). "We also examined NOX4 levels in patients with respiratory diseases according to their use of a ventilator." (PMID 35346198, 2022).
head and neck tumors (1 paper, 2021).
intestinal disease (1 paper, 2020). "Here we assess NOX4 expression in CD patients with inflammatory or stricturing disease and examine whether loss of NOX4 is beneficial in acute and fibrotic intestinal disease." (PMID 33059312, 2020). "Elevated NOX4 expression and H2O2 generation have been linked to acute and chronic inflammation in the vasculature, heart, lung, and liver, but the impact of NOX4 on intestinal disease and the development of fibrotic strictures is not known." (PMID 33059312, 2020).
peripheral neuropathy (1 paper, 2022). A disorder affecting the peripheral nervous system. "Nox4 has also been implicated in chemotherapy-induced peripheral neuropathy, because the downregulation of Nox4 suppressed the upregulation of TRPA1 in the spinal cord in a model of oxaliplatin-induced peripheral neuropathy." (PMID 35740059, 2022).
vasculopathies (1 paper, 2019). "NAD (P) H oxidases are the major sources of intracellular ROS production in Hcy-induced endothelial cells and NAD (P) H oxidases consist of multiple subunits, containing membrane-associated Nox1–4 and p22phox subunits, with Nox4 playing the key role in vasculopathies." (PMID 30315526, 2019). "NADPH oxidase enzymes are the primary sources of vascular ROS, with Nox4 playing the key role in vasculopathies and p22phox is a modulatory isoform for NADPH oxidase." (PMID 30315526, 2019).
NOX4 also shares sentences with these, for which no sentence is quoted: coronary artery disease (4 papers); alcoholic cardiomyopathy (3); anaplastic thyroid carcinomas (3); Hepatic steatosis (3); hypertensive nephropathy (3); pancreatic ductal adenocarcinoma (3); acute lung injury (2); acute myocardial infarction (2); acute respiratory distress syndrome (2); adenocarcinoma (2); Anal fistula (2); Arrhythmia (2); Arthritis (2); bladder urothelial carcinoma (2); deafness (2); endometrial cancer (2); essential hypertension (2); Glomerular sclerosis (2); hypertrophic cardiomyopathy (2); infarction (2); intervertebral disc degeneration (2); liver (2); neurotoxicity (2); oligodendroglioma (2); pterygium (2); retinopathy of prematurity (2); acute liver failure (1); anaplastic astrocytoma (1); anemia (1); atopic dermatitis (1).
A further 73 diseases each share a sentence with NOX4 in 1 paper.